E2F7 (E2F transcription factor 7)
Diseases named in the same sentence as E2F7 in open-access papers (continued):
Sharing a sentence is not in itself a finding about the gene and the disease.
tumor (continued). "ChIP‐sequencing data from ENCODE (Encyclopedia of DNA Elements) revealed clear binding peaks for E2F7 at promoter area of EZH2 in K562 tumor cells." (PMID 32064771, 2020). "In this cancer, E2F7-driven upregulation of SK1 is associated with anthracycline resistance; inhibition of E2F7 activity reduced SK1 levels and sensitized tumor cells to anthracycline chemotherapies." (PMID 33171624, 2020). "The majority of genes in the PAC-5 signature (LAMA3, E2F7, SLC12A2, and LRIG1) have been reported to be associated with tumour progression in various types of cancer." (PMID 31703415, 2019). "In this context, E2F7 was highly expressed in HCC tissues when compared with normal liver tissues, and high levels of E2F7 in tumor tissues had poor prognostic values on the OS of HCC patients." (PMID 30326936, 2018). "Deregulated E2F7 activity in cancer would thus be expected to impact on tumour cell growth both through its ability to modulate E2F1 activity as well as by influencing protein production through altered Pol I activity." (PMID 29760477, 2018). "The results showed that the gene expression and protein level of E2F7 was gradually and significantly increased during formation of tumor spheres in HepG2 and Huh7 cells." (PMID 30326936, 2018). "Additionally, E2F3 and E2F7, which are both involved in promoting tumor proliferation and inhibiting apoptosis, exhibited increased expression in high-risk NB, further emphasizing their role in tumor progression." (PMID 40599792, 2025). "Multiple studies have demonstrated the tumor-promoting effect of E2F7 in PCa." (PMID 39590378, 2024). "E2F7 is a known transcriptional factor and acts as a tumor promoter in various cancer." (PMID 39192374, 2024). "In conclusion, miR-5100 is a tumor suppressor in PCa by blocking cell cycle and targeting E2F7." (PMID 39590378, 2024). "Additionally, this study explored the effect of E2F7 knockdown affects tumor growth and metastasis, both in vivo and in vitro, aiming to improve the early detection of cisplatin-resistant LUAD and support tailored treatment strategies." (PMID 38760774, 2024). "Thus, E2F7 promoted BC cell progression, and miR-432-5p functioned as a tumor inhibitor in BC via targeting E2F7." (PMID 39192374, 2024). "Future work will delve into E2F7's role in the cisplatin-resistant LUAD tumor environment." (PMID 38760774, 2024). "In vitro experiments suggested that E2F7 plays a tumor suppressor role in GC cells." (PMID 39613162, 2024). "In addition, the relations between the selected gene (AQP7 and E2F7) and tumor immune features also analyzed." (PMID 37091789, 2023). "The findings above suggested that E2F7 was an effective enhancer of HCC tumor growth, and E2F7 might be a potential breakthrough for HCC‐targeted study." (PMID 35924788, 2022). "E2F7 is believed to promote tumor progression in various cancers as the target of miRNA-302a/d." (PMID 35531101, 2022). "Furthermore, in TP OPC and NFO, E2F7, which is found to be amplified in some tumours and controls the cell cycle by binding to RB1, is the downregulated eminent TF regulator." (PMID 34976314, 2022). "Finally, we need further experiments to explore the role of E2F7 in tumor progression and its mechanism of affecting tumors." (PMID 35984189, 2022). "It was reported that overexpression of E2F7 correlated with poor prognosis and microRNA-935 could inhibit tumor metastasis and invasion by targeted suppression the level of E2F7 in NSCLC." (PMID 36091687, 2022). "And depletion of E2F7 led to significant impairment of cell proliferation and tumor growth." (PMID 35924788, 2022). "Our results show that E2F7 is highly expressed in tumor tissues of HCC patients." (PMID 35444695, 2022). "In addition, high expression of circ-AASDH was found to participate in the tumor size, clinical stage and regulate the expression level of E2F7 by sponging miR-140-3p, which involves in the malignant progression of LUAD." (PMID 36205594, 2022).
tumor (continued). "Furthermore, a mechanism study suggested that the tumor-suppressive function of miR-26a in PCa was achieved through targeting E2F7." (PMID 35201478, 2021). "Besides, the expressions of p-AKT and p-mTOR in the tumours formed by E2F7-knockdown cells were decreased compared with the control cells, whereas the expression of PTEN was significantly increased." (PMID 32814835, 2020). "In addition to these genes that directly regulate tumor-microenvironment and desmoplasia, the top targets identified from our dataset consisted of the two additional genes E2F7 and MYBL2, which play essential roles in cell cycle regulation." (PMID 32660466, 2020). "The E2F7 expression was remarkably positively related to tumor purity (r = 0.151, P = 9.03e − 04), B cells (r = 0.222, P = 9.06e − 07), CD8+ T cells (r = 0.279, P = 5.13e − 10), macrophages (r = 0.199, P = 1.29e − 05), and DCs (r = 0.175, P = 1.22e − 04) in LGG." (PMID 33381564, 2020). "Nevertheless, the restored expression of EZH2 could reactivate AKT/mTOR pathway in the tumours formed by E2F7-silencing cells." (PMID 32814835, 2020). "In contrast, tumor growth is enhanced by the downregulation of inhibitory E2F transcription factors such as E2F4 and E2F7, and such an imbalance may cause a switch from cell quiescence to growth promotion." (PMID 31929759, 2020). "On the other hand, E2F7/8 suppresses tumour angiogenesis via the induction of DLL4." (PMID 31878977, 2019). "It is worthwhile to further define potential targets of E2F7, which may differentially regulate cell growth and motility in divergent tumour cells." (PMID 29540696, 2018). "MiR-30a-5p attenuates the EMT and metastasis in GBC cells by targeting E2F7, suggesting miR-30a-5p is a tumour suppressor that may serve as a novel potential prognostic biomarker or molecular therapeutic target for GBC." (PMID 29540696, 2018). "E2F7 siRNA blocked tumour cell growth, while E2F7 overexpression induced cell growth." (PMID 29540696, 2018). "Interestingly, in our study, we identified E2F7 as a tumour-promoting protein, as it can induce tumour cell proliferation, invasion and metastasis, and also has the ability to rescue tumour invasive behaviour inhibited by miR-30a-5p in GBC." (PMID 29540696, 2018). "E2F7 is a transcription factor which, in contrast to the other members of E2F family, has been shown to act as a repressor of several genes known to promote tumor cell proliferation." (PMID 20003503, 2009). "Furthermore, E2F7 was confirmed as a downstream target of miR-432-5p, and overexpression of E2F7 could rescue anti-tumor activity of miR-432-5p overexpression in BC cells." (PMID 39192374, 2024). "Furthermore, our data suggest that targeting E2F7, a cell-cycle-regulated gene modulated by miR-5100, directly may lead to significant anti-tumor effects." (PMID 39590378, 2024). "Importantly, upon evaluating the effect of overexpression of both miRNA-302a/d and E2F7 on the model of HepG2 and Huh7 tumor cells subcutaneously implanted in nude mice, our results showed that overexpression of E2F7 abolished the effects of miRNA-302a and miRNA-302d." (PMID 30326936, 2018). "E2F7 promotes the proliferation, motility, and invasion of CRC cells and enhances the functionality of CRC tumor stem cells, while E2F1 exhibits tumor-suppressive functions in CRC." (PMID 40842994, 2025). "Higher E2F1/E2F7 mRNA ratios were correlated with poor prognosis, whereas higher E2F7/E2F1 mRNA ratios were correlated with good prognosis, further supporting the oncogenic role of E2F1 and the tumor suppressor role of E2F7 in GC." (PMID 39613162, 2024). "Taken together, the data from the tumor xenografts support that E2F1 and E2F7 transcriptionally activate and repress MYBL2 to promote and inhibit GC cell proliferation, respectively." (PMID 39613162, 2024). "The expression of E2F7, MMP2 and Nanog was decreased in tumor tissues with sh-circFKBP8#1 transduction." (PMID 39192374, 2024).
tumor (continued). "TCGA database analysis revealed that E2F7, CD82, and TNNC1 showed significantly higher expression in tumor tissues than in normal tissues." (PMID 36612299, 2023). "And miR‐383‐5p, a posttranscriptional regulator discovered in our previous research as a tumor suppressor in HCC, was predicted as a potential bridge that mediates the regulation of E2F7 on SP1." (PMID 35924788, 2022). "It was reported that E2F7 transcriptionally regulated the VEGFR2 signaling pathway and induced HCC angiogenesis and tumor proliferation." (PMID 35924788, 2022). "In summary, as the atypical member of the E2F family, E2F7 facilitates HCC cell proliferation and tumor growth." (PMID 35924788, 2022). "Overall, these data demonstrate that E2F7 and E2F8 clearly contribute to the tumor formation in the pituitary glands of Rb+/− mice, while in the thyroid glands, loss of atypical E2Fs does not have a significant impact on RB loss dependent tumorigenesis." (PMID 33922435, 2021). "Recent studies have confirmed our conclusion: E2F7 has been proven to overexpressed in LUAD, and its expression is regulated by SNHG6 through the competitive sponging of miR-26a-5p, which promotes tumor growth and metastasis." (PMID 33042838, 2020). "Via qRT‐PCR, we found that silencing of E2F7 induced significant reduction of EZH2 mRNA expression in U87 and U373 tumor cells." (PMID 32064771, 2020). "Promoting the angiogenesis and the tumor proliferation, the complex MYLK-AS1/miR-424-5p activated the VEGFR-2 signaling through E2F7, whereas the specific targeting of E2F transcription factor 7 (E2F7) by miR-424-5p, was indicated by the mechanism studies." (PMID 33168027, 2020). "HeLa and C-33 A cells were cultured in serum-free medium for 5 days for spheroid formation, and we found that the diameter of tumor microspheres in sh-E2F2- and sh-E2F7-transfected HeLa and C-33 A cells was shorter than that found in the control group." (PMID 33061852, 2020). "Given the better performance of E2F7 and E2F8 in predicting patient outcome, we further explored the oncogenic role of E2F7 and E2F8 in HGG tumor cells." (PMID 32064771, 2020). "In terms of DFS, patients with increased E2F1 (p < 0.001), E2F2 (p < 0.001), E2F7 (p < 0.001), and E2F8 (p = 0.001) tumor expression have a poorer prognosis." (PMID 33061852, 2020). "Collectively, these data suggest E2F7 is involved with multiple oncogenic process and a potentially key regulator of EZH2 transcriptional activity in HGG tumor cells." (PMID 32064771, 2020). "To validate the essential role of CREB3L1, E2F7, FOXM1, and NFYB in ATC progression, we detected their gene expression levels in both human tumor tissues and cell lines." (PMID 31183379, 2019). "In the circPRKCI-silenced subcutaneous and orthotopic A172 xenograft tumor tissues, miR-545 levels were significantly upregulated, correlating with downregulation of its targets, RIG-1 and E2F7." (PMID 31409777, 2019). "E2F7 and E2F8 act as tumor suppressors via transcriptional repression of genes involved in S‐phase entry and progression." (PMID 31475738, 2019). "In the present study, E2F7 and E2F8 were significantly overexpressed in LC tissues, and their expression levels were markedly correlated with the tumor stage of the patients with LC." (PMID 29754146, 2018). "E2F7 is involved in resistance to therapy, while EPHA2 is overexpressed in a substantial number of tumors and promotes metastasis by stimulating tumor cell migration, invasion, and angiogenesis." (PMID 25122487, 2014). "In addition, circFKBP8 silencing significantly inhibited the protein levels of E2F7, KI-67, MMP2 and Nanog in tumor tissues." (PMID 39192374, 2024). "Importantly, our data demonstrated for the first time that E2F7 transcriptionally repressed MYBL2 in GC cells and that the tumor suppressive role of E2F7 on GC cells was partly dependent on its transcriptional repression of MYBL2." (PMID 39613162, 2024).
tumor (continued). "Our study unveils the molecular and cellular basis underlying SCLC’s high metastatic potential, the previously unrecognized role of YAP in suppressing ameboid migration and tumor metastasis, and the mechanism of YAP transcription regulation involving E2F7, RCOR, and Sin3 HDAC." (PMID 37739954, 2023). "Additionally, SNHG12, E2F7, p/t-MEK, and p/t-ERK expression pattern in tissues was reduced prominently whereas miR-129-5p expression pattern was increased when tumor-bearing mice were treated with EVs-sh-SNHG12 in comparison to EVs-sh-NC." (PMID 35383161, 2022). "We then investigated the relationships between the eight E2Fs and tumor immunology and found that E2F1, E2F3, E2F5, E2F6, and E2F7 expression was positively correlated with many immune cells, which might explain their favorable prognostic value." (PMID 34617871, 2021). "Our findings revealed that E2F7 protein was transported outside the HCC cells, maybe by exosomes, acting on the tumor microenvironment to increase the angiogenesis of the HCC tissue, enhancing the metastasis and proliferation of the HCC cells." (PMID 33168027, 2020). "In addition, this study highlighted the role of MYLK-AS1 as a ceRNA in the binding of miR-424-5p and that the upregulation of E2F7 resulted in the increased activation of VEGFR-2 signaling pathway, promoting tumor angiogenesis, proliferation, and metastasis." (PMID 33168027, 2020). "In addition, we found E2F7 and E2F8 demonstrated much higher correlation with VIM, a crucial epithelial‐mesenchymal transition (EMT) marker in tumor cells." (PMID 32064771, 2020). "miR-545 targets, E2F7 and RIG-1, were downregulated in circPRKCI-silenced orthotopic tumor tissues." (PMID 31409777, 2019). "In the analysis between the tumour tissues, mRNAs of LAMA3, E2F7, and IFI44 were more expressed in the tissues of the high-risk group than in those of low-risk group, whereas the expression levels of IFI44 and LRIG1 were lower in the high-risk group than in low-risk group." (PMID 31703415, 2019). "Moreover, the E2F7 and E2F8 expressions were positively related to tumor purity in GBM remarkably." (PMID 33381564, 2020). "However, E2F7 expression analysis by qRT-PCR demonstrated that its expression levels were significantly higher in 154 HCC tumor biopsies relative to adjacent non-neoplastic tissues." (PMID 30326936, 2018). "Moreover, our results showed that E2F7 expression was negatively correlated with miRNA-302a/d expression in both normal liver tissues (n = 34, R2 = 0.48 and 0.52, respectively) and HCC tumor biopsies (n = 154, R2 = 0.63 and 0.66, respectively)." (PMID 30326936, 2018). "Thus, it would be of great interest to investigate whether E2F7/8 not only control CCBE1 and FLT4 during developmental lymphangiogenesis but also during tumor dissemination." (PMID 24069224, 2013). "Furthermore, we followed by RT-PCR the expression of four selected genes, namely Pten, Hmox1, E2f7 and Nod1 in LLC as well as in other cancer cell lines of human origin, in order to reveal potential common patterns of response to mastic oil among different tumor types." (PMID 20003503, 2009). "While E2F7 was not significantly related with immune, stromal, and ESTIMATE scores, and tumor purity." (PMID 37091789, 2023). "E2F7 cooperated with CBFB-recruited RUNX1 in a non-canonical manner to transactivate ITGA2, ITGA5, and NTRK1, strengthening Akt signaling-induced tumor-promoting effect." (PMID 37028765, 2023).
tumor (continued). "The results showed that the expression levels of E2F2, E2F3, E2F6, and E2F8 are significantly correlated with the tumor stage of PAAD patients, while the expression levels of E2F1, E2F4, E2F5 and E2F7 are not correlated with the tumor stage of PAAD patients." (PMID 33604289, 2020). "Similarly, HCC patients with high E2F7 expression and low miRNA-302d levels had significantly decreased OS (P < 0.001) and PFS (P < 0.001), which suggested that E2F7 and miRNA-302a/d might have potential prognostic value and could be useful as tumor biomarkers for the diagnosis of HCC patients." (PMID 30326936, 2018). "In addition, although LAMA3 and E2F7 did not exhibit direct interactions with proteins involved in resistance to EGFR-TKIs, these two proteins were also connected to many proteins related to tumour progression." (PMID 31703415, 2019).